B3GNT6 (UDP-GlcNAc:betaGal beta-1,3-N-acetylglucosaminyltransferase 6)
Description:
Beta-1,3-N-acetylglucosaminyltransferase that synthesizes the core 3 structure of the O-glycan, an important precursor in the biosynthesis of mucin-type glycoproteins. Plays an important role in the synthesis of mucin-type O-glycans in digestive organs.
Synonyms: BGnT-6; Beta-1,3-Gn-T6; Beta3Gn-T6; B3Gn-T6
Tractability: Antibody: UniProt predicts a signal peptide or a membrane-spanning region.
Target class: Enzyme; Transferase
Gene: Protein-coding gene on chromosome 11 (77,034,398 to 77,041,973, forward strand). Ensembl gene ENSG00000198488.
Subcellular location: Golgi apparatus membrane
Pathways (Reactome):
Metabolism of proteins: O-linked glycosylation of mucins
Gene Ontology:
Molecular function: galactosyltransferase activity; acetylgalactosaminyl-O-glycosyl-glycoprotein beta-1,3-N-acetylglucosaminyltransferase activity; beta-1,3-galactosyl-O-glycosyl-glycoprotein beta-1,3-N-acetylglucosaminyltransferase activity; UDP-glycosyltransferase activity; acetylglucosaminyltransferase activity; hexosyltransferase activity
Biological process: glycoprotein biosynthetic process; poly-N-acetyllactosamine biosynthetic process; protein O-linked glycosylation via N-acetyl-galactosamine
Cellular component: Golgi membrane; membrane
Genetic constraint (gnomAD): Missense variants: 624 observed, 500.53 expected, observed/expected ratio (o/e) 1.25, 90% interval 1.17 to 1.33. Synonymous variants: 300 observed, 234.27 expected, observed/expected ratio (o/e) 1.28, 90% interval 1.16 to 1.41.
Homologues: Orthologues: chimpanzee B3GNT6 (99% identical), macaque B3GNT6 (94% identical), dog B3GNT6 (79% identical), rabbit B3GNT6 (78% identical), pig B3GNT6 (77% identical), guinea pig B3GNT6 (73% identical), rat B3gnt6 (70% identical), mouse B3gnt6 (70% identical), tropical clawed frog XB5969542 (34% identical), zebrafish b3gnt7l (33% identical), zebrafish si:dkey-160o24.3 (32% identical), zebrafish si:dkey-175m17.6 (31% identical), and 14 more. Paralogues in human: B3GNT3 (48% identical), B3GNT9 (38% identical), B3GNT7 (37% identical), B3GNT4 (36% identical), B3GNT2 (34% identical), B3GNT8 (31% identical), B3GALT2 (26% identical), B3GNT5 (26% identical), B3GALT4 (25% identical), B3GALT1 (23% identical), B3GALT5 (22% identical), B3GALT6 (22% identical), and 3 more.
Diseases named in the same sentence as B3GNT6 in open-access papers:
B3GNT6 is named in the same sentence as 16 diseases in open-access papers, as found by Europe PMC text mining. Sharing a sentence is not in itself a finding about the gene and the disease. The quoted sentences say what the papers report.
colorectal cancer (9 papers, 2014 to 2026). A primary or metastatic malignant neoplasm that affects the colon or rectum. "Survival analysis showed that the downregulation of B3GNT6 mRNA expression was associated with a low overall survival rate of patients with colorectal cancer." (PMID 35387659, 2022). "The downregulation of B3GNT6 mRNA expression in colorectal cancer tissues is related to CIN status, KRAS mutation, and proteasome pathway." (PMID 35387659, 2022). "Gene set enrichment analysis (GSEA) revealed that low B3GNT6 expression levels in colorectal cancer were associated with increased proteasome activity." (PMID 35387659, 2022). "Downregulation of B3GNT6 expression was found to be associated with poor overall survival in patients with colorectal cancer as per the data in GSE39582 and TCGA databases." (PMID 35387659, 2022). "Studies have found that B3GNT6 is closely related to a variety of disease processes, such as immunity deficiency, colorectal cancer and m6A modification, Together, these results indicate that B3GNT6 may be the downstream target of IGF2BP2." (PMID 35908253, 2023). "Conversely, B3GNT6 is predominantly expressed in the proximal colon, regulates core 3 O-glycan formation and its knockout causes increased susceptibility to colitis and colorectal cancer." (PMID 37070602, 2023). "Data from TCGA, GSE37182, and GSE39582 datasets revealed that B3GNT6 expression could be used as a good diagnostic marker for colorectal cancer with statistical significance." (PMID 35387659, 2022). "Functional experiments further revealed that B3GNT6 expression was downregulated in tumors and inhibited colorectal cancer proliferation, migration, tumor growth, and metastasis." (PMID 42212317, 2026). "Herein, we conducted an in-depth bioinformatics analysis using online databases to investigate the mRNA and protein expression patterns of B3GNT6 and its clinical significance in colorectal cancer." (PMID 35387659, 2022). "To measure B3GNT6 mRNA levels in colorectal cancer tissues, we first analyzed B3GNT6 mRNA levels by comparing mRNA levels in the tumor tissues compared with that in normal or para-tumor tissues in GSE37182, GSE39582, and GSE103512." (PMID 35387659, 2022). "Results indicated that in the GI tract, the stomach, esophagus, and normal colorectal tissues, B3GNT6 mRNA levels were higher than those in colorectal cancer tissues; however, the small intestine showed low B3GNT6 expression." (PMID 35387659, 2022). "B3GNT6 expression was downregulated in colorectal cancer tissues as compared to that in the normal tissues at both mRNA and protein levels." (PMID 35387659, 2022). "Low B3GNT6 mRNA levels were significantly associated with chromosome instability (CIN) and KRAS mutations in patients with colorectal cancer." (PMID 35387659, 2022). "Immunohistochemical analysis of B3GNT6 protein expression was also conducted in 43 paired tissues from our own cohort of colorectal cancer patients." (PMID 35387659, 2022). "Next, we examined B3GNT6 expression with regard to its prognostic significance in colorectal cancer." (PMID 35387659, 2022). "To further address the change in B3GNT6 expression and its clinical significance in patients with colorectal cancer, we analyzed the online databases of protein expression together with our own clinical cohorts." (PMID 35387659, 2022). "B3GNT6 mRNA expression levels were negatively correlated with overall survival in patients with colorectal cancer." (PMID 35387659, 2022). "We speculated that B3GNT6 might negatively regulate the occurrence and metastasis of colorectal cancer through the KRAS/ERK signal pathway." (PMID 35387659, 2022). "Together, these findings indicate that high B3GNT6 expression has clinical significance and could potentially serve as an important biomarker for predicting clinical outcomes in patients with colorectal cancer." (PMID 35387659, 2022).
colorectal cancer (continued). "This is interesting because it may clarify the role of B3GNT6 expression in the development of colorectal cancer." (PMID 35387659, 2022). "Negative (5/43) or weakly positive (30/43) or positive (8/43) staining of B3GNT6 protein was observed in colorectal cancer tissues when compared to the weakly positive (5/43) or positive (27/43) staining or strongly positive (11/43) staining in paired adjacent non-tumor tissues." (PMID 35387659, 2022). "B3GNT6 expression has been reported to be largely downregulated in gastric and colorectal cancers." (PMID 35387659, 2022). "We conducted a bioinformatic analysis of GEO and TCGA datasets as well as our own cohort and found that the mRNA and protein levels of B3GNT6 in colorectal cancer tissues were significantly lower than those in the normal tissues, which was consistent with the results of previous studies." (PMID 35387659, 2022). "Additionally, the altered expression of β-catenin/TCF-4, c-myc, and cyclin D1 was observed during chemical-induced carcinogenesis, suggesting a possible role of B3GNT6 KO in human colorectal carcinoma." (PMID 32075174, 2020). "In addition to mucins, also the core 3 synthase, acetylgalactosaminyl-O-glycosyl-glycoprotein beta-1,3-N-acetylglucosaminyltransferase, encoded by the B3GNT6 gene in humans, has been reported to be significantly down-regulated in colorectal cancer samples." (PMID 31091244, 2019). "Negative (11/12) or low (1/12) staining of B3GNT6 protein was observed in colorectal cancer tissues when compared to the medium staining in normal colon (3/3) and rectal tissues (3/3)." (PMID 35387659, 2022). "We also conducted immunohistochemical analyses in 43 colorectal cancer tissues with paired adjacent non-tumor tissues, which also showed downregulation of B3GNT6 protein expression in colorectal cancer." (PMID 35387659, 2022).
colon carcinoma (6 papers, 2011 to 2023). "Although this study highlights the role of the B3GNT6 gene on colon cancer, the underlying mechanism or specific glycoprotein involved in this process is not yet identified." (PMID 32075174, 2020). "Moreover, the association between KCNMA1, B3GNT6, and colon cancer needs to be explored further." (PMID 36944972, 2023). "Then, we analysed the expressions of CLCA1, UGT2A3 and B3GNT6 in 480 cases of colon cancer and 41 cases of adjacent tissues in the TCGA database and their effects on survival and metastasis." (PMID 36855796, 2023). "To confirm whether G4‐CSSD590 can restore the expression of CLCA1, UGT2A3 and B3GNT6 and its role in colon cancer after the adsorption of miR‐590‐3p, we transfected Ctrl CSSD, CSSD590 and G4‐CSSD590 in HCT116 and Caco‐2 cells." (PMID 36855796, 2023). "Another study delineated the role of B3GNT6 in colon cancer." (PMID 32075174, 2020). "To verify the role of CLCA1, B3GNT6 and UGT2A3 in colon cancer, we overexpressed these genes in HCT‐116 and Caco‐2 colon cancer cells and tested their cell phenotype, proliferation, migration and invasion ability." (PMID 36855796, 2023). "We found three candidate core, tumour, suppressor genes in colon cancer, namely, CLCA1, B3GNT6 and UGT2A3." (PMID 36855796, 2023). "We discovered new colon cancer related genes including AC007952.4, NEK8, CHRM3, ANO7, B3GNT6, NEURL1, ODC1 and KCNMA1." (PMID 36944972, 2023). "After repressing miR‐590‐3p with G4‐CSSD590, the upregulation of CLCA1, B3GNT6 and UGT2A3 inhibited the proliferation and metastasis of colon cancer cells." (PMID 36855796, 2023). "In colon cancer, we observed the simultaneous low expressions of chloride channel accessory 1 (CLCA1), UDP‐GlcNAc:betaGal beta‐1,3‐N‐acetylglucosaminyltransferase 6 (B3GNT6) and UDP glucuronosyltransferase family 2 member A3 (UGT2A3), which indicated an favourable prognosis." (PMID 36855796, 2023).
colitis (4 papers, 2016 to 2025). Inflammation of the colon. "In murine models, knockout of the core 3 O-glycan–synthesizing enzyme B3GNT6 leads to a marked reduction in Muc2 mucin in the colonic mucosa, increased intestinal permeability, and greater susceptibility to colitis and colorectal tumorigenesis following pathogenic challenge or chemical injury." (PMID 41301470, 2025). "In contrast, B3gnt6-deficient mice, which lack the core 3 O-glycan, did not develop spontaneous colitis but displayed heightened susceptibility to dextran sulfate sodium (DSS)-induced experimental colitis because of a weakened mucus barrier." (PMID 39589551, 2024). "EPR cKO mice, whose phenotype is more evident in the proximal colon where B3GNT6 is predominantly expressed, display normal levels of C1GALT1 and, as in B3GNT6 knockout, colitis is only apparent upon DSS challenge." (PMID 37070602, 2023).
adenoma (2 papers, 2021 to 2023). A neoplasm arising from the epithelium. "We collected the resected carcinoma tissues from CRC patients and conducted immunohistochemical (IHC) staining analysis to examine the expression of some representative genes including NEK8, CHRM3, ANO7, B3GNT6, NEURL1, ODC1 and KCNMA1 in colon normal tissue, adenoma tissue and carcinoma tissues." (PMID 36944972, 2023).
pancreatic cancer (2 papers, 2023). "As the stabilizers of m6A methylation, IGF2BP2 and IGF2BP3 can enhance the stability of B3GNT6 and spermine synthase (SMS) mRNA and protein expression, respectively, to promote the progression of pancreatic cancer." (PMID 36981005, 2023).
prostate carcinoma (2 papers, 2017 to 2021). A carcinoma that arises from epithelial cells of the prostate gland. "Increased B3GNT6 expression has previously been reported in prostate cancer, and it may be involved in the metastatic capacity of cancer cells." (PMID 28467780, 2017). "By contrast, the β3-N-acetylglucosaminyltransferase-6 (B3GNT6) modifies core 3 O-glycan leading to decreased levels of the α2β1 integrin, decreased activation of focal adhesion kinase and lamellipodia formation which, in turn, suppresses tumor formation and metastasis of prostate carcinoma." (PMID 34646995, 2021).
autoimmune disease (1 paper, 2024). A disorder resulting from loss of function or tissue destruction of an organ or multiple organs, arising from humoral or cellular immune responses of the individual to their own tissue constituents. "B3GNT6, which encodes an important precursor in the biosynthesis of mucin-type glycoproteins, is associated with autoimmune diseases and DNA repair, such as selective lgA deficiency." (PMID 38400850, 2024).
breast carcinoma (1 paper, 2011). "We, therefore, looked by RT-qPCR at the expression of β3GNT6 in 58 Stage 1 and Stage 2 breast carcinomas." (PMID 21385452, 2011). "However, in only 3 out of 58 breast carcinoma samples was a β3GNT6 transcript detectable and these were at least 100-fold lower than the glycosyltransferase, C1GALT1, that competes for the same sugar substrate to form core 1 (T)." (PMID 21385452, 2011). "We found that the β3GNT6 transcript could only be detected in 3 of 58 breast carcinomas, and even then the level was at least 100-fold lower than the competing glycosyltransferase, C1GALT1." (PMID 21385452, 2011).
cholangiocarcinoma (1 paper, 2022). A carcinoma that arises from the intrahepatic biliary tree (intrahepatic cholangiocarcinoma) or from the junction, or adjacent to the junction, of the right and left hepatic ducts (hilar cholangiocarcinoma). "Boottanun and colleagues reported that the low expression of B3GNT6 is associated with higher differentiation and better prognosis in patients with cholangiocarcinoma." (PMID 35387659, 2022).
meningioma (1 paper, 2024). A generally slow growing tumor attached to the dura mater. "In the GEO database, the respective mRNA expressions of C1GALT1, COSMC, C2GNT1, C2GNT2, and B3GNT6 was highly expressed in Grade I, Grade II, and Grade III meningiomas." (PMID 38274327, 2024).
tumor (10 papers, 2017 to 2026). "The roles of B3GNT6-associated tumor progression have been demonstrated in pancreatic, prostatic, colon, and colorectal cancer." (PMID 38274327, 2024). "B3GNT6 mRNA levels were significantly lower in tumor tissues than those in normal tissues in all three microarrays." (PMID 35387659, 2022). "In tumor environments, downregulation of B3GNT6 expression may lead to upregulation of proteasome activity, which in turn suppresses the accumulation of misfolded or toxic proteins in tumor cells." (PMID 35387659, 2022). "Clinical patient samples were used to perform gene expression analysis from normal pancreata, matched liver metastatic sites, and tumor tissues to reveal the differential expression pattern of Core-3 synthase (B3GnT-6), as well as additional glycosyltransferases." (PMID 32075174, 2020). "In this study, a high expression of B3GNT6 was found in 19 of 44 (43%) tumor samples." (PMID 28467780, 2017). "After the measurement of tumour size, the solid tumour tissue was fixed in formalin solution to detect the expressions of CLCA1, UGT2A3 and B3GNT6." (PMID 36855796, 2023). "Some of the glycoTs genes such as GCNT3, GALNT5, FUT3, B3GNT6 and B3GNT3 were more than 19-fold overexpressed in tumour samples." (PMID 32203219, 2020). "Using a cut-off of 1.5-fold change, the expression levels of these four genes were down-regulated in CCA tissues compared to non-tumor tissues, evidenced by the percent of tumor cases showing high expression of C1GALT1–29% (26/90), COSMC–7% (6/90), B3GNT6–7% (15/90), and ST6GALNAC1–24% (22/90)." (PMID 35207462, 2022). "For instance, B3GNT6 is highly expressed in the ACER3-B3GNT6 positive tumor samples, and almost absent in both the fusion-negative tumor samples (p = 9.9E-12) and benign samples (p = 2.1E-13, Wilcoxon rank-test)." (PMID 28467780, 2017).
cancer (8 papers, 2015 to 2024). A tumor composed of atypical neoplastic, often pleomorphic cells that invade other tissues. "While many knockdown studies for Core-3 synthase have been reported for other cancers, the overexpression analysis of B3GNT6 was conducted in PCa." (PMID 32075174, 2020). "This gene encodes B3GNT6 protein, the absence of which predisposes to the development of chronic inflammation and ultimately to the development of cancer." (PMID 38400850, 2024). "B3GNT6 is only expressed in the normal gastrointestinal tract and downregulated in cancer, and interestingly, B3GNT6 is not expressed in common cancer cell lines." (PMID 35247390, 2022).
infection (1 paper, 2025). The state of being infected such as from the introduction of a foreign agent such as serum, vaccine, antigenic substance or organism. "Validation by RT-qPCR confirmed significant upregulation of B3GNT6 and MUC5AC genes and downregulation of the SPRR gene family following BpWT infection." (PMID 40757824, 2025).
B3GNT6 also shares sentences with these, for which no sentence is quoted: Familial adenomatous polyposis (1 paper); immunity deficiency (1); pancreatic ductal adenocarcinoma (1).